TRAV38-2DV8 (T cell receptor alpha variable 38-2/delta variable 8)
Description:
V region of the variable domain of T cell receptor (TR) alpha chain that participates in the antigen recognition. Alpha-beta T cell receptors are antigen specific receptors which are essential to the immune response and are present on the cell surface of T lymphocytes. Recognize peptide-major histocompatibility (MH) (pMH) complexes that are displayed by antigen presenting cells (APC), a prerequisite for efficient T cell adaptive immunity against pathogens. Binding of alpha-beta TR to pMH complex initiates TR-CD3 clustering on the cell surface and intracellular activation of LCK that phosphorylates the ITAM motifs of CD3G, CD3D, CD3E and CD247 enabling the recruitment of ZAP70. In turn ZAP70 phosphorylates LAT, which recruits numerous signaling molecules to form the LAT signalosome. The LAT signalosome propagates signal branching to three major signaling pathways, the calcium, the mitogen-activated protein kinase (MAPK) kinase and the nuclear factor NF-kappa-B (NF-kB) pathways, leading to the mobilization of transcription factors that are critical for gene expression and essential for T cell growth and differentiation. The T cell repertoire is generated in the thymus, by V-(D)-J rearrangement. This repertoire is then shaped by intrathymic selection events to generate a peripheral T cell pool of self-MH restricted, non-autoaggressive T cells. Post-thymic interaction of alpha-beta TR with the pMH complexes shapes TR structural and functional avidity.
Synonyms: TRAV38-2/DV8; TRAV382DV8; TCRAV14S1; hADV38S2
Tractability: Antibody: UniProt places it where antibodies can reach, with medium confidence; UniProt predicts a signal peptide or a membrane-spanning region; its Gene Ontology location is reachable by antibodies, with medium confidence.
Gene: T-cell receptor variable (V) gene on chromosome 14 (22,281,105 to 22,281,748, forward strand). Ensembl gene ENSG00000211817.
Subcellular location: Cell membrane
Gene Ontology:
Biological process: immune response
Cellular component: immunoglobulin complex; plasma membrane
Homologues: Orthologues: chimpanzee TRAV38-2DV8 (83% identical), mouse Trdv2-2 (70% identical), tropical clawed frog trac (32% identical). Paralogues in human: TRAV38-1 (87% identical), TRAV5 (34% identical), TRAV13-1 (33% identical), TRAV21 (33% identical), TRAV17 (31% identical), TRAV13-2 (30% identical), TRAV6 (30% identical), TRAV36DV7 (28% identical), TRAV20 (28% identical), TRAV25 (28% identical), TRAV26-2 (28% identical), TRAV10 (27% identical), and 10 more.